FOXP3 (forkhead box P3)
Diseases named in the same sentence as FOXP3 in open-access papers (continued):
Sharing a sentence is not in itself a finding about the gene and the disease.
melanoma (continued). "More recent clinical data from lung, breast, pancreatic, hepatocellular, and urinary bladder cancer as well as melanoma provided first evidence for a Foxp3 expression also in tumor cells." (PMID 23382847, 2013). "It has been described that in pancreatic cancers or in melanoma, FOXP3 expression is restricted to the tumor cells." (PMID 24350059, 2013). "In pancreatic carcinoma and in melanoma, FOXP3 has a tumor-enhancing role through Treg and their effect on tumor tolerance; in ovarian, breast and prostate cancer, FOXP3 has a tumor-suppressing function." (PMID 23888189, 2012). "We tested the association of variants in FOXP3 microsatellites, CTLA4 SNPs and HLA genotype in 284 melanoma patients and their association with prognosis and survival of melanoma patients who received IFNa adjuvant therapy." (PMID 22911710, 2012). "Our group already recently reported that quantitation of Foxp3 expression using quantitative PCR appears as an independent prognostic factor for PFS in stage III melanoma patients with invaded lymph nodes." (PMID 23284620, 2012). "Cyclophosphamide has been shown to deplete Tregs and boost the efficacy of vaccines in mouse models and CpG, which targets the toll-like receptor 9, reduces FoxP3+ cells in the lymph nodes of melanoma patients." (PMID 21281484, 2011). "As also reported in other tumor models we found that even small B16.OVA melanoma tumors contained higher frequencies of CD25+ Foxp3+ Treg than blood, and that tumor-infiltrating Treg had suppressive activity in vitro." (PMID 21390236, 2011). "This was analyzed in more detail in only one of the reports with the combination of CD127 and FOXP3 being the most appropriate combination to identify Treg cells in patients with malignant melanoma." (PMID 21904560, 2011). "The expression of FOXp3 was twofold lower (ratio 0.53); however, DCs in lymph nodes with advanced melanoma metastasis have a higher expression of IDO than primary skin tumours (ratio 1.63)." (PMID 17565341, 2007). "FoxP3-positive cells were present as single positive cells within the lymphatic tissue in SLN as well as among tumour cells in primary melanoma of the skin." (PMID 17565341, 2007). "CD4+ FOXP3+ T regulatory cells may make up a higher proportion of the CD4+ T cell compartment in melanoma compared to normal skin." (PMID 39825956, 2025). "Indeed, we observed an accumulation of FoxP3+ iNKTreg cells within melanoma tumors, a disturbed NCR/NKG2 profile, and a skewed ICP expression toward LAG3, CTLA4, and TIM3, which were associated with early relapse and shorter survival." (PMID 41562072, 2025). "In primary melanoma, low FOXP3 TIL counts have shown improved survival." (PMID 39883679, 2025). "CD4+ T FOXP3+ T regulatory cells are present in the primary melanoma TIME." (PMID 39825956, 2025). "Moreover, FOXP3 expression has been reported in tumor cells themselves, including breast, prostate, and melanoma, further contributing to immune evasion and adverse outcomes." (PMID 41150760, 2025). "Alongside this, there was a notable involvement of FOXP3+ Tregs (regulatory T cells) in melanoma." (PMID 40386779, 2025). "Treg FoxP3 expression may be used as an independent prognostic factor in patients with malignant melanoma to evaluate tumor progression and survival." (PMID 38928083, 2024). "Additionally, in this study, as PAK4 expression was linked to immune cell infiltration, IDO1 expression was similarly correlated with PD-L1 expression and the infiltration of FOXP3-positive cells in melanoma." (PMID 39273017, 2024). "In addition, we analyzed the percentage of Foxp3-expressing CD4+ T cells infiltrating B16 melanoma tumors in these mice." (PMID 39272810, 2024). "The biological explanation for these contradictory findings between melanoma, renal, lung carcinoma, and colorectal cancer remains unclear, but we can see a similar pattern between increased infiltration of FoxP3+ Tregs and OS." (PMID 36980787, 2023).
melanoma (continued). "As CTLA-4 inhibitors reduce the number and function of Tregs in malignant melanoma, the positivity of FoxP3 could help in the decision-making process between monotherapy with PD-1 inhibitors and combination therapy with PD-1 and CTLA-4 inhibitors." (PMID 36980787, 2023). "The results of in vivo treatment in melanoma-bearing mice resulted in significant inhibition of tumor growth due to the alterations in the tumor microenvironment, which lead to a decrease in melanoma infiltration by M2 as well as PD-1+ and FoxP3+ cells." (PMID 37345057, 2023). "We examined melanoma patient-derived B cells in B:T-helper cell ex vivo co-cultures to evaluate whether these supported induction of FOXP3+ CD4+ regulatory T cells (Tregs)." (PMID 35909944, 2022). "In addition, AIL suppressed PD-L1 transcription through the AIL-c-Jun-PD-L1 pathway in melanoma cells, consequently blocking PD-L1 secretion, resulting in Treg inhibition and Foxp3 expression reduction, and ultimately enhancing the efficacy of PD-L1 blockade." (PMID 36522774, 2022). "Furthermore, CD8+ CTLs associated positively with IDO+ stromal immune and melanoma cells and tumor nest CD68+ macrophages, but only weakly with FoxP3+ Tregs and total macrophage counts." (PMID 36551965, 2022). "The study was carried out on C57Bl/6 FoxP3-EGFP mice bearing B16F0 melanoma." (PMID 36555468, 2022). "In addition, IDO1/TDO activation causes kynurenine (Kyn) accumulation in the TME, which activates the aryl hydrocarbon receptor (AhR), orienting T-cell differentiation into FoxP3+ regulatory T cells and the resultant melanoma immune escape." (PMID 36003368, 2022). "It has been reported that CTLA-4 siRNA-loaded nanoparticles could increase the number of CD8+ T cells, decrease the ratio of CD4+ FOXP3+ Tregs and effectively inhibited tumor growth in mice with melanoma." (PMID 34875483, 2022). "Increased number of VISTA+ lymphocytes has been detected in patients afflicted by metastatic melanoma and VISTA expression is positively correlated with intratumoral nuclear expression of FOXP3+ Tregs and melanoma suppresses the immune system responses via upregulating FOXP3+ Tregs." (PMID 32902664, 2021). "Moreover, we found that patients with melanoma showed strong positive correlation between FOXP3 and IFNB1 expression." (PMID 34751648, 2021). "Furthermore, another analysis of 209 advanced melanoma patients showed that baseline levels of low Lin−CD14+HLA−DR−/low-MDSCs and high CD4+CD25+FoxP3+-Tregs, were significantly associated with better survival." (PMID 35008245, 2021). "However, the expression and function of FoxP3 in cancer cells is contradictory, since in pancreatic cancer and melanoma it is expressed in the tumor cells whereas it is present in the normal epithelial cells in human breast and prostate cancer." (PMID 34900746, 2021). "Similarly, enrichment of CD8+NKG2D+ effector T cells and decrease in CD4+CD25+FOXP3+ Tregs were observed in B16 melanoma as well as NBL tumors." (PMID 34721405, 2021). "Moreover, the therapeutic response can be affected by several parameters, such as the mutational load of GATA3+ cells, FOXP3+ cells and CD33+ cells and the abundance of TILs in lung cancer or melanoma." (PMID 34221962, 2021). "The positive association of FoxP3+ Tregs with IDO+ melanoma cells, but not with IDO+ stromal immune cells, indicates a complex interaction between IDO and Tregs in CM, which demands further studies." (PMID 34051744, 2021). "The presence of CTLA4+ Tregs in tumors and CTLA4– Tregs in adjacent tissues is in line with observations that anti‐CTLA4 therapies may target FOXP3+ Tregs to induce tumor rejection in melanoma." (PMID 34185431, 2021). "FOXP3 staining of human melanoma biopsies revealed similar increases in Tregs in young patients." (PMID 34947849, 2021). "Also, this seems to be a peculiar pathway of immunity in melanoma, since in other tumors, there is a functional cross-talk between dendritic cells and FOXP3 regulatory T cells." (PMID 33274240, 2020).
melanoma (continued). "FOXP3 is probably a useful therapeutical target in melanoma, since inhibition of FOXP3-positive tumor clones and of regulatory T cells could eliminate the ability of tumor cells to escape the immune defense of the host." (PMID 33274240, 2020). "Moreover, other immune cells presented higher CD68 (M0 macrophages), and Foxp3 (Tregs) expression in melanoma tissues than in healthy skin tissues." (PMID 32931642, 2020). "Low SIAH2 and FOXP3 expression is identified in immune responsive human melanoma tumors." (PMID 31911617, 2020). "As such, the clinical validation of Immunoscore as a prognostic and predictive biomarker (for ICB) in these other tumor types are still underway while additional TIL markers such as CD20 and FOXP3 have also been included in evaluating the Immunoscore in melanoma." (PMID 33013886, 2020). "A positive correlation between SIAH2 and FOXP3 (Tregs marker) expression suggests that findings derived from a genetic murine melanoma model are relevant to human tumors and that low Siah2 levels could serve as a marker to stratify patients for ICT therapy." (PMID 31911617, 2020). "A recent study showed that the enrichment of the feces with C. aerofaciens and B. longum in melanoma patients, who received anti-PD1 treatment, is associated with an increased frequency of CD8+ T cells and reduced Foxp3+CD4+ Tregs in the tumor microenvironment." (PMID 32295112, 2020). "Foxp3, a key regulator of immune suppression, is expressed by both melanoma cells and Tregs." (PMID 31690033, 2019). "Interestingly, melanoma expresses TGF-β-induced forkhead box P3 transcription factor (Foxp3), which functions as an intracellular molecular marker of Tregs." (PMID 31690033, 2019). "Similarly, tumor derived MVs from both HNSCC and melanoma sera induce in vitro expansion of CD4+CD25+FoxP3+ with enhanced suppressor function." (PMID 31681327, 2019). "Consequently, the peripheral and intra-tumoral expansion of CD4+/CD25+/Foxp3+ cells correlates directly with melanoma progression." (PMID 31750245, 2019). "The PD-1-blocking antibody pembrolizumab has been shown to elicit an increased proliferation of both, Foxp3-negative and Foxp3-positive CD4 as well as CD8 T cells in stage IV melanoma patients, displaying the most significant effects in the PD-1 expressing cells of these populations." (PMID 29032503, 2018). "Furthermore, the proposed method successfully analyzed an independent data set, showing that the same FOXP3+ subpopulation was increased in melanoma patients, validating the method." (PMID 26864030, 2016). "To establish the method, we used a data set of PBMCs from melanoma patients and healthy controls (HCs), which previously identified that total FOXP3+ T cells increased in melanoma patients, and that FOXP3low naive Tregs and FOXP3low non-Tregs increased as the stage progressed." (PMID 26864030, 2016). "Several types of non-lymphoid tumour cells are reported to have up-regulated FOXP3 expression in the cell nucleus, including pancreas, melanoma, and epithelial cells of papilloma virus associated cervical cancer." (PMID 27160146, 2016). "By analyzing flow cytometric data of melanoma patients, the proposed method showed that the FOXP3+ subpopulation that had relatively high FOXP3, CD45RO, and CD25 expressions was increased in melanoma patients, whereas manual gating did not produce significant results on the FOXP3+ subpopulations." (PMID 26864030, 2016). "Furthermore, in this study, we have newly obtained a flow cytometric data set of FOXP3+ T cells from melanoma patients and HCs (designated as the second data set), to address the efficiency of the proposed method." (PMID 26864030, 2016). "Moreover, melanoma cells programmed to undergo EMT can promote immune escape by generating CD4+FOXP3+ regulatory T cells and impairing dendritic cell maturation, both in vitro and in vivo." (PMID 27764776, 2016).
melanoma (continued). "However, none of these studies systematically addressed the percentage of melanomas which express FOXP3, or the percentage of FOXP3+ cells within melanomas." (PMID 24406338, 2014). "However, eight out of the nine stably transfected melanoma cell lines demonstrated increased FOXP3 expression in <30% of cells." (PMID 24406338, 2014). "However, previous studies have demonstrated that Foxp3 was also expressed in tumor cells, such as pancreatic cancer, melanoma and other tumor cell lines." (PMID 24932293, 2014). "Therefore, it is possible that over-expression of FOXP3 and the subsequent modification of gene expression perturbed normal cell functions in melanoma cells, leading to induction of stress response pathways." (PMID 24406338, 2014). "Interestingly, for most samples, we were also able to detect low-level FOXP3 expression in the bulk melanoma cell population, detected as a shift in fluorescence intensity compared to the fluorescence-minus-one (FMO) control." (PMID 24406338, 2014). "It is widely accepted that FoxP3 is expressed not only in mice and humans but also in tumor cells such as melanoma stomach and might have relationship with immunosuppressive effect." (PMID 24707483, 2014). "The aim of the current study was to characterize the expression and function of FOXP3 in melanoma." (PMID 24406338, 2014). "The expression of Foxp3 was detected in the B16F10 melanoma cells at the mRNA and protein levels." (PMID 24179494, 2013). "Foxp3 expression has been reported in a variety of solid human tumors, including melanoma." (PMID 24179494, 2013). "On the one hand, it has been shown that FOXP3 expression in melanoma cells or in pancreatic carcinoma cells renders the tumor cells suppressive with Treg-like activity to directly inhibit the proliferation of T cells and suggesting a possible mechanism of tumor resistance to immune system." (PMID 24350059, 2013). "However, the regression of the melanoma growth, which was induced by depletion of Foxp3+ Tregs, was critically dependent on the presence of CD8+ T cells in this model and additional elimination of those cells resulted in ongoing tumor progression." (PMID 22890822, 2013). "From these data, it may be suggested that Foxp3 participates in melanoma growth, the modulation of the IL-2, IFN-γ and TNF-α cytokines and CD25 expression, and that it also plays a possible role in immunosuppression." (PMID 24179494, 2013). "In this study, we sought to investigate whether functional inactivation of CD4+CD25+FoxP3+ Treg with anti-CD25 monoclonal antibody (mAb) PC61 prior to DC/tumor vaccination would significantly improve immunotherapy in the murine B16 melanoma model." (PMID 23768240, 2013). "In addition, the expression of the alpha chain of the IL-2 receptor (CD25) and the nuclear transcription factor Foxp3 was significantly increased in the melanoma tissue specimens from advanced stage III." (PMID 23284620, 2012). "Thus, we tested the association of variants in FOXP3 microsatellites, CTLA4 SNPs and HLA genotype in 284 melanoma patients and their association with prognosis and survival of patients with melanoma who received adjuvant therapy with IFNa." (PMID 22911710, 2012). "However, recent publications indicate that increased FOXP3 expression in CD8+ T cell serves as a good prognosis marker in melanoma patients undergoing high does IL-2 combined with peptide vaccination therapy." (PMID 22911710, 2012). "A recent report found that in melanomas, FOXP3 is also expressed by tumor-reactive CD8+ T cells." (PMID 23888189, 2012). "Finally, FOXP3 is a marker for Treg cells, which are associated with negative outcomes for melanoma patients." (PMID 40573917, 2025). "Importantly, cytotoxic CD8+ T cells versus CD4+Foxp3+ regulatory T cells ratio may have predictive value for melanoma outcome." (PMID 38920557, 2024).
melanoma (continued). "Therefore, we tested whether melanoma cell secretome-mediated CTLA4 downregulation is regulated at the transcriptional level through FOXP3 in Treg cells." (PMID 37197667, 2023). "Notably, Tregs induced Foxp3 expression in melanoma cells with higher invasiveness and metastatic potential, suggesting that Foxp3 may play a pivotal role in Treg-induced metastasis." (PMID 31690033, 2019). "Conversely, we could not detect significant gene expression differences for most of these genes (e.g., pHMGB1 > 0.9) in melanoma cells, or expression was barely detected at all (average transcripts per million < 1), see E2A in B lymphocytes or FOXP3 and TBET in T lymphocytes, for instance." (PMID 29662057, 2018). "Therefore, we generated Treg-replete tumor-bearing mice by subcutaneous thigh injection of OVA-expressing B16 melanoma (0.5×106 cells per mouse) into DEREG (Foxp3-DTR) mice that express diphtheria toxin (DT) receptor-enhanced green fluorescent protein under control of the Foxp3 promoter." (PMID 28496990, 2017). "Here we show that reducing sialic acids on the surface of melanoma cells evokes the generation of large numbers of effector T cells that infiltrate the tumor area and simultaneously dampens the intra-tumoral presence of Foxp3+ Tregs, together curtailing tumor growth." (PMID 26741508, 2016). "In addition, our group did not identify any mutations in FOXP3 in a panel of 54 early passage melanoma cell lines or well-established breast and prostate cancer cell lines." (PMID 24406338, 2014). "Thus, Foxp3 appears overall as a predictive marker for immunological approaches in melanoma." (PMID 24741578, 2014). "Thus the mechanism by which FOXP3 inhibits growth of melanoma cells appears distinct." (PMID 24406338, 2014). "In addition, FOXP3 has been reported to be expressed in many tumors, including melanoma." (PMID 24406338, 2014). "The aims of the present study were to analyze Foxp3 expression in B16F10 melanoma cells in vitro, to determine whether this expression was affected during tumor growth in a murine melanoma model and to correlate Foxp3 expression with CD25 expression, interleukin (IL)-2 production and tumor weight." (PMID 24179494, 2013). "Although Tregs are the major cell type expressing FOXP3, it has recently been demonstrated that the tumor cell itself can express FOXP3, such as pancreatic cancer, melanoma and other tumor types, and the function of FOXP3 may represent a new mechanism of immune evasion in cancers." (PMID 23759077, 2013). "Furthermore, the expression of IDO has been correlated with an increase of Foxp3+ cells in multiple murine models, in human pancreatic adenocarcinoma, in human uterine cervical carcinoma, and in humans with advanced stages of melanoma following vaccination." (PMID 19604349, 2009). "We here suggest that it is the subset of melanoma metastases with lower CD8 TIL counts that showed the lowest values of the two immunosuppressive markers tumour cell PD-L1 expression and FOXP3 count." (PMID 39883679, 2025). "Here, we investigated the impact on survival for CD3, CD8, FOXP3 and PD-L1 TIL counts and tumour PD-L1 expression in melanoma loco-regional metastases." (PMID 39883679, 2025). "Using this technique, we developed a seven-color lymphocyte panel to detect different lymphocyte populations within tissue consisting of CD3, FOXP3, CD8, CD45RO, CD20, a tumor marker (such as pan-cytokeratin or a melanoma-specific antibody cocktail), and DAPI." (PMID 39866377, 2025). "Here, we examined the prognostic impact of CD3, CD8, FOXP3 and PD-L1 TIL counts and of tumour PD-L1 expression in melanoma loco-regional metastases." (PMID 39883679, 2025). "Unlike treatment of radiosensitive MC38 tumors, RT led to an increase in the numbers of FOXP3+ Tregs, resulting in a decreased TIL/Treg ratio in both B16 and BRaf/Pten melanoma tumors." (PMID 40146036, 2025).